TIMP1 (TIMP metallopeptidase inhibitor 1)
Diseases named in the same sentence as TIMP1 in open-access papers (continued):
Sharing a sentence is not in itself a finding about the gene and the disease.
colorectal cancer (continued). "In light of previous scientific inquiries, it’s compelling to mention that many of the genes within this list of 10, specifically CAV1, DAPK1, GPX3, IGFBP6, TIMP1, GADD45B and ENO2 have been found associated intimately with colorectal cancer, as documented by several research studies." (PMID 38501104, 2024). "TIMP1 plays a role in conferring resistance to ferroptosis in colorectal cancer cells." (PMID 38562143, 2024). "We selected three candidate colorectal cancer biomarkers (B2M, TIMP-1, and CLU)." (PMID 36792801, 2023). "Specifically, in CRC tissues with high TIMP1 expression, there is a higher proportion of M2 macrophage infiltration, implying that TIMP1 may promote the development of colorectal cancer by increasing M2 macrophage infiltration." (PMID 37842645, 2023). "In colorectal cancer, TIMP1 promotes metastasis through the FAK-PI3K/AKT and MAPK pathways." (PMID 36765702, 2023). "Considering the significant potential of TIMP1 in the diagnosis and prognosis of colorectal cancer, it is crucial to determine whether it can serve as a viable drug target." (PMID 37842645, 2023). "However, for a comprehensive understanding of the unique significance of TIMP1 in colorectal cancer development, systematic bioinformatics analysis is required to delve deeper into its role in the cancer progression." (PMID 37842645, 2023). "Consequently, we conclude that TIMP1 holds the highest potential value in the diagnosis and prognosis of colorectal cancer." (PMID 37842645, 2023). "TIMP1 was recognized as a serum biomarker of colorectal cancer through meta-analysis." (PMID 35778451, 2022). "Recent studies have proved that TIMP1 and TGA2B mRNA in TEPs and a three‐platelet mRNA set (MAX, MTURN, and HLA‐B) may be used as a diagnostic biomarker for colorectal cancer and lung cancer." (PMID 33955587, 2021). "Presence of TIMP1 mRNA in platelet independently predicts the presence of colorectal cancer." (PMID 34907282, 2021). "In another study, rutin could not hinder the development of AOM-induced rat colon cancer and augmented tissue inhibitor of metalloproteinase 1 (TIMP-1) expression, a biomarker of colorectal cancer progression." (PMID 32823876, 2020). "Additionally, TIMP1 mRNA expressed in platelets from colorectal cancer patients can be carried into colorectal cancer cells, where it promotes tumor growth in vivo and in vitro." (PMID 31639773, 2019). "One of these factors could be tissue inhibitor of metalloproteinase 1 (TIMP-1) as TIMP-1 is involved in different cellular survival functions and has been associated with decreased chemo-sensitivity in breast and colorectal cancer." (PMID 29523123, 2018). "Few studies concern the prognostic value of MMP-8, MMP-9, or TIMP-1 in colorectal cancer." (PMID 29929486, 2018). "In several TIMP-1 biomarker studies, the TIMP-1 protein levels have been measured in pre-operative blood samples and it has been demonstrated that plasma TIMP-1 in breast and colorectal cancer are significantly associated with tumor grade as well as patient survival." (PMID 27619981, 2016). "Therefore, TIMP-1 appears to be a novel marker for detection of early colorectal cancer and for prognostic stratification of colorectal cancer patients." (PMID 15785755, 2005). "Overexpression of TIMP-1 has been reported in colorectal cancer tissues." (PMID 15785755, 2005). "The mean level of TIMP-1 in EDTA plasma from 143 patients with Dukes' stage D colorectal cancer was 240 ± 145 μg l−1 and a Mann–Whitney test demonstrated a highly significant difference between TIMP-1 levels in healthy blood donors and colorectal cancer patients (P < 0.0001)." (PMID 10408859, 1999). "In summary, CRC-derived TIMP1 can induce macrophage M2 polarization, facilitating immune evasion and remodeling the liver microenvironment to establish a pre-metastatic niche, thereby enhancing the survival and colonization capacity of colorectal cancer cells in the liver." (PMID 41511313, 2025).
colorectal cancer (continued). "Therefore, we utilized the DepMap database to predict which drugs might be more effective in treating colorectal cancer patients with high TIMP1 expression." (PMID 37842645, 2023). "Serum MMP-8 and TIMP-1 may serve as prognostic factors in colorectal cancer." (PMID 29929486, 2018). "Significantly increased serum TIMP-1 levels and a potential poor prognostic role have been reported in patients with melanoma, and patients with a variety of cancer types including breast, prostate, gastric, colorectal carcinoma, glioblastoma, and multiple myeloma." (PMID 24457057, 2014). "These images showed that AQP8 and NR5A2 exhibited low staining intensity in colorectal cancer tissues, whereas SCD and TIMP1 showed high staining intensity." (PMID 41438584, 2026). "We evaluated the activity of MMPs in the murine colorectal cancer SL4 cell line to examine the effect of MMPs on the balance between MMPs and TIMP1." (PMID 38830933, 2024). "In this study, we conducted differential gene expression analysis on three GEO datasets and confirmed SPP1, MMP1, CXCL8, CXCL1, TIMP1, MMP3, and CXCL10 as core regulatory genes in colorectal cancer through a protein-protein interaction network." (PMID 37842645, 2023). "TIMP1 and TNFRSF1B genes have been confirmed to take part in the pathogenesis of colorectal cancer and have prognostic value." (PMID 35480305, 2022). "Their data suggest that MMPs, as well as their inhibitors TIMP-1 and TIMP-2, play a crucial role in colorectal cancer." (PMID 36250005, 2022). "In colorectal cancer, high serum MMP-8 levels and high blood neutrophil and leukocyte count correlated positively, but correlations between TIMP-1 and white blood cell count were less clear." (PMID 29929486, 2018). "In contrast, in a study on 180 patients, of whom 75 had colorectal cancer, MMP-9 and TIMP-1 levels were higher in colorectal cancer patients than in healthy controls or in colorectal adenoma patients." (PMID 29929486, 2018). "In colorectal cancer, we found that high levels of serum MMP-8 and TIMP-1 serve as prognostic factors." (PMID 29929486, 2018). "Previous studies comparing ELISA values to PEA for biomarkers of colorectal cancer (CEA, IL-8, TIMP-1 and CA242) found correlations ranging from 0.73 to 0.98." (PMID 29051715, 2017). "The median TIMP-1 level as well as the narrow range is rather low when compared to studies describing plasma TIMP-1 levels in breast and colorectal cancer using the same method and laboratory." (PMID 27619981, 2016). "We also analysed the relationship between TIMP-1 levels and CEA, which is well recognized and still the only recommended marker used in the diagnosis and follow-up of patients with colorectal cancer." (PMID 23801910, 2013). "Serum TIMP1 levels show promise as a prognostic marker for colorectal cancer and correlate with systemic inflammatory markers, but do not correlate with TIMP1 expression in tumor tissue." (PMID 39789100, 2025). "To assess whether TIMP1-driven liver metastasis depends on T cells, we implanted CT26 or MC38 colorectal cancer cells stably overexpressing TIMP1 into BALB/c nude mice, which lack functional T cells." (PMID 41511313, 2025). "Ulcerative colitis is recognized as a precancerous condition for colorectal cancer (CRC), yet the specific mechanism by which TIMP1 mediates the malignant progression of CRC through modulation of ferroptosis remains unclear." (PMID 40687427, 2025). "Therefore, in this scenario, TIMP1-induced activation of the PI3K/Akt pathway and subsequent upregulation of GPX4 contribute to resistance against sorafenib-triggered ferroptosis in colorectal cancer cells." (PMID 38562143, 2024). "In colorectal cancer, elevated levels of systemic tissue inhibitors of metalloproteinases (TIMP) metallopeptidase inhibitor 1 (TIMP-1) trigger hepatic stellate cells to release chemokines, such as C-X-C motif chemokine 12 (CXCL12), that recruit neutrophils to the liver." (PMID 34202272, 2021).
colorectal cancer (continued). "In addition, upregulated TIMP1 in the cancerous CAF stroma would participate the vascular remodeling process and enhance the invasions of colorectal cancer cells." (PMID 34670584, 2021). "Presented genes, especially ADAM17, MMP9, EphA2, TIMP1, ICAM 11, and CD4, may be used as prognostic markers of advanced stages of colorectal cancer, contributing to the development of new lines of therapy focused on reducing metastasis of the primary tumor." (PMID 27110571, 2016). "In colorectal cancer cell line Caco-2 IP6 modulated MMP-2, TIMP-1, and TIMP-2 genes expression." (PMID 22415590, 2012). "Drug sensitivity analysis, conducted using the DepMap database, revealed that colorectal cancer cell lines exhibiting elevated levels of TIMP1 expression were more responsive to certain drugs, such as CC-90003, Pitavastatin, Atuveciclib, and CT7001, compared to those with low levels of TIMP1." (PMID 37842645, 2023). "Moreover, colorectal-cancer-derived and TIMP-1-enriched extracellular vesicles were recently found to upregulate TIMP-1 levels in recipient liver fibroblasts and induce ECM remodeling, which could be a precursor event in the establishment of a metastatic niche in the liver." (PMID 37443843, 2023). "This is supported by studies in primary breast- and colorectal cancer where lack of correlation between tumour tissue TIMP-1 levels and blood levels of TIMP-1 have been published." (PMID 20459644, 2010).
lung carcinoma (88 papers, 2004 to 2026). "included TIMP1 as a component of an 8‐marker panel to accurately identify subjects with stage I lung cancer from high‐risk smokers using a proteomic analysis." (PMID 37759102, 2023). "Although several studies demonstrated that the inhibition of TIMP1 promotes angiogenesis, there are also contradictory works reporting on enhanced tumor angiogenesis in the brain metastasis of lung carcinoma associated with TIMP-1 overexpression." (PMID 35326438, 2022). "In particular, alterations in TIMP-1 and MMP-9 levels have been observed in subjects with lung cancer compared to controls, associated with a poor prognosis, indicating a possible role of TIMP-1 and MMP-9 as a prognostic marker." (PMID 32392801, 2020). "High serum and tissue expression of TIMP-1 is associated with poor prognosis and decreased survival for several cancers including lung cancer." (PMID 31443242, 2019). "siRNA approaches revealed cisplatin-induced expression and subsequent release of tissue inhibitor of matrix metalloproteinases-1 (TIMP-1) by lung cancer cells to be causally linked to a decrease in HUVEC migration and tube formation." (PMID 30344920, 2018). "However, previous studies have suggested that high circulating levels of TIMP1 are associated with unfavorable prognosis in lung cancer." (PMID 37759102, 2023). "TCGA analysis showed TIMP-1 is associated with energy metabolism in lung cancer." (PMID 36230997, 2022). "The elevated TIMP-1 level was also associated with poor prognosis in lung cancer." (PMID 14960203, 2004). "Serum TIMP-1 levels were significantly higher in individuals with prevalent and incident cancer, including colorectal and lung cancer, whereas lower MMP-8 levels were observed in colorectal and prostate cancer." (PMID 42162053, 2026). "Tissue inhibitor of metalloproteinases 1 (TIMP1) serves as an early detection and prognosis biomarker for aggressive lung cancer—its serum level correlates with tumor burden and survival in mice, and has been validated in clinical samples." (PMID 40943297, 2025). "(2012) found that CBD inhibits lung cancer cell invasion by inducing tissue inhibitor of metalloproteinases-1 (TIMP-1) through intercellular adhesion molecule-1 (ICAM-1) activation." (PMID 40599866, 2025). "Rab37 mediates the exocytosis of tissue inhibitor of metalloproteinase 1 (TIMP1) in a nucleotide-dependent way to disrupt MMP9 migration in lung cancer." (PMID 38695990, 2024). "Patients suffering from lung cancer with metastasis and poor survival demonstrates that decreased expression levels of Rab37 are consistent with low TIMP1 expression in lung tumors." (PMID 38695990, 2024). "Unexpectedly, these findings are inconsistent with the observations that aberrant upregulation of TIMP1 correlated to malignant progression and poor prognoses in numerous cancers, such as breast, liver, and lung cancer." (PMID 38770133, 2024). "Research has shown that amiodarone-induced secretory autophagy enhances Timp1 secretion, inhibiting lung cancer cell movement both in vivo and in vitro." (PMID 38728287, 2024). "RAB37 dependent secretory autophagy participates in TIMP1 secretion in lung cancer both in vitro and in vivo." (PMID 38804615, 2024). "We reveal that activated Rab37 promotes the secretion of insulin in mouse β cells (Min‐6) and TIMP1 in human lung cancer cells (CL1‐5‐Q89L, harboring active Rab37), respectively." (PMID 38804615, 2024). "We recently reported that Rab37 is involved in secretory autophagy to mediate TIMP1 secretion in lung cancer cells." (PMID 38778059, 2024). "Similar to what we observed in the mice, TIMP1 was significantly increased in individuals with lung cancer compared to the healthy control group or subjects with other non‐malignant thoracic pathologies." (PMID 37759102, 2023).
lung carcinoma (continued). "This prompted us to further assess which cells from the tumour microenvironment contribute to the production of TIMP1 using a previously published single‐cell RNA‐Seq data set from human lung cancer." (PMID 37759102, 2023). "To validate the results found in the KL mice, we measured the concentration of TIMP1 in the plasma of healthy donors, patients with other non‐malignant thoracic pathologies, and patients with lung cancer." (PMID 37759102, 2023). "In previous work, the researchers found cisplatin to induce tissue inhibitor of matrix metalloproteinase-1 (TIMP-1) secretion from lung cancer cells." (PMID 37593220, 2023). "A statistically significant correlation was observed between lower TIMP1 gene expression and longer survival of patients with lung cancer (p < 0.001)." (PMID 37509417, 2023). "We performed a discovery screen in a well‐established murine model of lung cancer and found that TIMP1 is highly expressed in the tumours of mice, reaching levels high enough in the serum to be used as an early detection biomarker." (PMID 37759102, 2023). "We further interrogated the expression of TIMP1 in lung cancer fibroblast subpopulations using a recently published single‐cell RNA‐Seq data set." (PMID 37759102, 2023). "TIMP1 levels correlated with tumour burden and predicted overall survival in mice and humans with lung cancer." (PMID 37759102, 2023). "In this study, we used a well‐established, genetically engineered mouse model of lung cancer to identify TIMP1 as a tumour‐secreted factor that predicts poor survival in mice and humans with lung cancer." (PMID 37759102, 2023). "Among the most interesting studies conducted in the last 10 years, CancerSEEK reported a panel of eight proteins (CA-125, CEA, HGF, Myeloperoxidase, OPN, Prolactin, and TIMP-1) effective in distinguishing lung cancer patients from healthy controls." (PMID 38068296, 2023). "We identified tissue inhibitor of metalloproteinase 1 (TIMP1) as an early biomarker and validated this finding in the plasma of lung cancer patients." (PMID 37759102, 2023). "The production of MMPs and TIMP-1 in lung cancer tissue derived cell lines, represented cancer clinical behavior." (PMID 36518397, 2022). "An anti-invasive effect based on TIMP-1 induction in lung cancer cells was also confirmed for the FAAH inhibitors N-arachidonoyl-serotonin (AA-5HT) and URB597, AEA and OEA as well as for the MAGL inhibitor JZL184 and the MAGL substrate 2-AG." (PMID 35277658, 2022). "Some studies reported the association between increased levels of MMP-2, MMP-9 and decreased TIMP-1 in early stage lung cancer." (PMID 36518397, 2022). "Herein, the effect of Smp24 on the viability, membrane disruption, cytoskeleton, migration and invasion, and MMP-2/-9 and TIMP-1/-2 expression of human lung cancer cells have been evaluated." (PMID 35878176, 2022). "A causal contribution of TRPV1 to the anti-invasive impact of R(+)-methanandamide on cervical and lung cancer cells was shown to be mediated by upregulation of TIMP-1." (PMID 31143113, 2019). "It was demonstrated that Rab-37 suppresses lung cancer metastasis by mediating TIMP1 (tissue inhibitor of metalloproteinase) exocytosis, which inactivates extracellular matrix metallopeptidase 9 (MMP9) and suppresses cell invasion signalling." (PMID 31370342, 2019). "Our investigations revealed knockdown of cisplatin-induced TIMP-1 in A549 cells to significantly inhibit the antimigratory impact of CM obtained from cisplatin-treated lung cancer cells on HUVECs (black bars)." (PMID 30344920, 2018). "Considering that cisplatin has been found to similarly induce TIMP-1 as part of its anti-invasive action on cervical and lung cancer cells, the present study addressed a probable TIMP-1-dependent antiangiogenic action of cisplatin at non-toxic concentrations." (PMID 30344920, 2018).